TTR (transthyretin)
Diseases named in the same sentence as TTR in open-access papers (continued):
Sharing a sentence is not in itself a finding about the gene and the disease.
preeclampsia (14 papers, 2014 to 2025). Preeclampsia is a hypertensive disorder of pregnancy that is characterized by new-onset hypertension with proteinuria presenting after 20 weeks of gestation, and depending on mild or severe forms may initially present with severe headache, visual disturbances, and hyperreflexia. "Systemic TTR is directly implicated in the multifactorial, hypertensive syndrome of preeclampsia, which affects 5–7% of pregnant women and is a leading cause of maternal death, severe maternal morbidity, and prematurity in the US." (PMID 40717228, 2025). "Aggregates of TTR found in the trophoblasts of placentas from mothers with preeclampsia are believed to be a contributory cause of the pathophysiology." (PMID 40717228, 2025). "Several amyloidogenic proteins, including amyloid-β, transthyretin, and α-1-antitrypsin, have been identified in the preeclampsia-associated misfoldome and proposed as potential diagnostic markers for preeclampsia." (PMID 39758342, 2024). "One consequence of this could be a reduction in the ability of TTR to bind to and protect the vascular system from soluble endoglin, an anti-angiogenic factor positively associated with preeclampsia pathogenesis." (PMID 40717228, 2025). "We were unable to demonstrate any association between maternal TTR serum levels and any pregnancy-associated morbidity, such as preeclampsia, but this might be related to our relatively small sample size, which was under-powered to show this." (PMID 35482459, 2022). "Although higher levels of TTR are usually an indicator of a better protein nutritional status, increased TTR has also been associated with disease, as in preeclampsia, where aggregated TTR, extruded into the maternal circulation via placental extracellular vesicles, was also reported." (PMID 32197355, 2020). "Here, we reported that transthyretin is found at increased levels in preeclamptic placentae compared to normotensive placentae, and that in preeclampsia, this transthyretin is aggregated and almost half of all transthyretin secreted by the placenta is associated with extracellular vesicles." (PMID 28751735, 2017). "Preeclamptic placentae secreted similar levels of total transthyretin compared to normotensive placentae (2352 ± 2949 ng/mL vs. 3250 ± 1864 ng/mL, mean ± SD, p > 0.05, n = 8), however in preeclampsia, a significant proportion is vesicle-associated (~48% vs 0%)." (PMID 28751735, 2017). "Mice engineered to overexpress human TTR while their endogenous murine TTR was silenced developed a preeclampsia-like phenotype when pregnant, and deposits of TTR aggregates were found in the placenta." (PMID 40717228, 2025). "Using a mouse model, TTR was identified as a key amyloidogenic protein involved in the pathogenesis of preeclampsia." (PMID 40717228, 2025). "TTR in serum from women with preeclampsia has shown a higher propensity to aggregate than TTR from women with healthy pregnancies." (PMID 40717228, 2025). "In one study, TTR expression was noted to be downregulated in syncytiotrophoblasts of placenta in women with preeclampsia compared with placentas from gestation-matched women with normal pregnancies." (PMID 40717228, 2025). "Future studies are required to investigate any potential disruption of thyroid function during preeclampsia following experimental studies that show disruption of transthyretin physiology and hepatic deiodinase activity." (PMID 37878891, 2024). "We identified that transthyretin, a transporter of thyroxine and retinol, was a key component in the protein complex in the preeclampsia placenta." (PMID 37626934, 2023). "Female rats were treated with N′‐nitro‐l‐arginine‐methylesterhydrochloride to establish a model of preeclampsia and subsequently treated with transthyretin." (PMID 32533762, 2020). "Elevated levels of aggregated transthyretin are formed in preeclampsia and transported through the secretion of placental extracellular vesicles by syncytiotrophoblasts." (PMID 30079067, 2018).
preeclampsia (continued). "Protein toxic aggregates such as aggregated transthyretin which, is a placental toxin elevated in preeclampsia, have been suggested to contribute to the pathogenesis of this disorder." (PMID 30079067, 2018). "Transthyretin isolated from preeclamptic serum is also aggregated and can induce preeclampsia-like symptoms in pregnant IL10−/− mice." (PMID 28751735, 2017). "In patients with preeclampsia (PE), a pregnancy disorder characterized by high blood pressure and proteinuria, dissociation of TTR tetramer leads to formation of partially unfolded monomers which aggregate to form amyloid fibrils." (PMID 29185488, 2017). "Although the expression of TTR in IUGR and preeclampsia is controversial, arguments are in favour of low TTR levels in IUGR/preeclampsia." (PMID 29185488, 2017). "In contrast, the mRNA levels of transthyretin in preeclamptic placentae were not altered, suggesting changes in the posttranscriptional processing of transthyretin, leading to its aggregation and packaging into placental nano-vesicles in preeclampsia." (PMID 28751735, 2017). "In preeclampsia, the placental production of this protein is affected at the post-transcriptional level and this in turn leads to increased packaging of aggregated transthyretin into placental nano-vesicles." (PMID 28751735, 2017). "This study showed that the placenta actively produces transthyretin and in preeclampsia, a significant amount is extruded into the maternal circulation via placental exracellular vesicles." (PMID 28751735, 2017). "This suggests that it is the posttranscriptional processing of transthyretin which is altered in preeclampsia, resulting in the increased protein levels observed." (PMID 28751735, 2017). "Finally, TTR dysregulation leading to TTR aggregates in the placenta contributes to the pathogenesis of preeclampsia." (PMID 40717228, 2025). "The question then arises of whether TTR dysregulation that commences during pregnancy in women with preeclampsia persists after delivery and, if so, for how long." (PMID 40717228, 2025). "TTR dysregulation has been shown to contribute to the pathogenesis of preeclampsia." (PMID 40717228, 2025). "Aberrant TTR from the serum of women with preeclampsia reproduced preeclampsia-like features in pregnant IL-10–/– mice (a high-inflammation rodent model), and these were rescued by the administration of exogenous native human TTR." (PMID 40717228, 2025). "In addition, the TTR aggregates eluted from preeclampsia sera induced preeclampsia-like features, hypertension, and proteinuria in interleukin (IL)-10 knockout mice." (PMID 33670947, 2021). "In preeclampsia, a complex and severe disorder of pregnancy, incorrect placental development was shown to be correlated with TTR levels, spatial distribution, and stability, and low levels of TTR were detected in the plasma and syncytiotrophoblasts." (PMID 34359938, 2021). "In serum samples from women with preeclampsia, surface-enhanced laser desorption ionization-time-of-flight, known as SELDI-TOF, revealed that TTR monomers in serum were significantly decreased during preeclampsia when compared with that in normal pregnant women." (PMID 33670947, 2021). "Importantly, TTR aggregation is responsible for preeclampsia development, and unaggregated TTR prevents the onset of a pathological phenotype." (PMID 34359938, 2021). "These lines of evidence suggest that transthyretin may be involved in the early pathogenesis of preeclampsia, however the source of pathological transthyretin remains unclear." (PMID 28751735, 2017). "In preeclampsia, the serum levels of transthyretin, a carrier protein for thyroxine, are elevated." (PMID 28751735, 2017). "Whether the packaging of aggregated transthyretin, and other protein aggregates, into placental nano-vesicles has functional consequences in the pathogenesis of preeclampsia remains to be determined." (PMID 28751735, 2017).
preeclampsia (continued). "Despite this evidence, it remains to be determined whether women harbouring pathogenic TTR variants have higher rates of preeclampsia or IUGR than those without pathogenic variants." (PMID 40717228, 2025). "It has also been suggested that preeclampsia serum-mediated disruption in the communication between endothelial cells and trophoblasts, and the subsequent impairment of capillary tube formation, can be rescued by the addition of native TTR in an in vitro model." (PMID 40717228, 2025). "Aggregated transthyretin in these vesicles may also allow targeted delivery of these toxic proteins to other maternal organs, conducting a signal of cellular stress from the diseased placenta and contributing to the pathogenesis of preeclampsia." (PMID 30079067, 2018). "Therefore, this study was undertaken to investigate whether human placentae produce altered levels of transthyretin in preeclampsia and whether transthyretin is carried from the placenta into the maternal circulation via extracellular vesicles." (PMID 28751735, 2017).
protein misfolding diseases (14 papers, 2019 to 2025). "We can also learn more about the potential effects of TTR misfolding from other TTR-associated proteinopathies." (PMID 38338354, 2024). "Under conditions of proteinopathy in the serum and human placenta in PE, we have demonstrated the presence of aggregated TTR, amyloid β, and cis P-tau proteins in the serum of patients with early- or late-onset severe PE16." (PMID 38760513, 2024). "Systemic ATTR amyloidosis is an increasingly important protein misfolding disease that is provoked by the formation of amyloid fibrils from transthyretin protein." (PMID 37993462, 2023).
Nephropathy (13 papers, 2004 to 2025). A nonspecific term referring to disease or damage of the kidneys. "It remains to be determined if this is limited to the excretion of TTR in pregnancy or if under other circumstances such as in different kidney diseases similar molecular variants occur as well." (PMID 15341658, 2004). "The excretion of substantial amounts of TTR has only been described in individuals with different kidney diseases indicating disturbed glomerular filtration and/or insufficient tubular reabsorption." (PMID 15341658, 2004). "Moreover, kidney amyloid deposits have been shown to remain stable even after 2 years from OLT and progression of nephropathy is theoretically possible because of continued amyloid deposition from wild-type TTR." (PMID 40630302, 2025). "Platelet-derived transthyretin (TTR) has been shown to play a role in kidney damage during sepsis." (PMID 39834999, 2024). "In addition, the binding of RBP4 to retinol and transthyretin (TTR) was affected by several factors (e.g. serum retinol, vitamin A intake, physical activity, protein-energy malnutrition, and liver and renal diseases)." (PMID 30038059, 2018).
atherosclerosis (12 papers, 2007 to 2023). A disease characterized by the build-up of fatty material and calcium deposition in the arterial wall resulting in partial or complete occlusion of the arterial lumen. "At the same time, an increase in the content of the monomeric form of transthyretin is associated with atherosclerosis." (PMID 34948066, 2021). "As we know, RBP4 is a predictor of endothelial dysfunction, atherosclerosis and other cardiovascular diseases and is a member of the lipocalin family, which is bound to vitamin A and transthyretin while being secreted into the circulation." (PMID 38069063, 2023). "Transthyretin is an indicator of inflammation and nutritional status, which makes it closely related to atherosclerosis." (PMID 36212641, 2022). "Because of the differences in pathogenesis between ICAS and ECAS, our results confirmed for the first time that a decrease in serum transthyretin also indicated atherosclerosis in the intracranial artery." (PMID 36212641, 2022). "Higher expression of TTR in the plaques in women suggests a functional role of TTR in sex-related differences in atherosclerosis." (PMID 34359938, 2021). "To further validate the disease-specificity of the three biomarkers, we examined serum levels for apoA-I, TTR and TF in 71 additional subjects that included normal, breast cancer, colon cancer, atherosclerosis, and early stage OC." (PMID 19662218, 2007). "It is of interest to determine whether TTR (directly or indirectly through HDL) regulates the MEG3/miR-223-3p/FBXW7/Notch1 signaling pathway in atherosclerosis." (PMID 34359938, 2021). "Therefore, in the following sections, the contribution of TTR to the pathogenesis of atherosclerosis and balance between fibrinolytic and coagulation systems are considered." (PMID 34359938, 2021). "MMP-2 and MMP-9 may also contribute to fibrous cap thinning and plaque rupture in atherosclerosis, indicating a possible role of TTR in cap stability." (PMID 34359938, 2021). "Additionally, prealbumin (transthyretin) is a hepatic secretory protein used to assess malnutrition in PD patients, and it is related to inflammation and atherosclerosis." (PMID 33238904, 2020). "Therefore, TTR may also play a protective role via LRP-1 receptor in atherosclerosis, especially because LRP-1 is involved in glucose homeostasis and inflammation, and binds HDL." (PMID 34359938, 2021). "By measuring the circulating retinol-binding protein 4 (RBP4), transthyretin (TTR) and the cIMT, a link between vitamin A and subclinical atherosclerosis was shown." (PMID 32283588, 2020).
cognitive decline (12 papers, 2015 to 2026). "Higher serum levels of vitamin A, vitamin D, TTR, albumin, Se, and UA could act as protective factors against cognitive decline, whereas higher BMI could act as a risk factor." (PMID 35686024, 2022). "Diminishing CNS TTR has been linked to cognitive decline with age." (PMID 25705176, 2015). "In AD, the stability and functionality of TTR seems compromised, possibly leading to an accumulation of Aβ fibrils and, subsequently, to neurodegeneration and cognitive decline." (PMID 39192044, 2025). "Evidence from animal models has shown the direct effects of TTR on memory, spatial learning, and cognitive decline." (PMID 40717228, 2025). "In blood analysis, the CGA group showed increased levels of apolipoprotein A1 and transthyretin, both of which are putative biomarkers for early-stage cognitive decline." (PMID 30241302, 2018). "Similarly, genetic deletion of TTR in mouse models accelerated Aβ plaque deposition and led to earlier cognitive decline, once more supporting its protective role." (PMID 41013670, 2025). "We hypothesized that plasma TTR levels may relate to the rate of cognitive decline and could be a predictor of MCI-to-AD conversion." (PMID 31822765, 2019). "Higher plasma TTR levels might reflect more rapid or larger amounts of Aβ accumulation, which might result in more rapid cognitive decline with time." (PMID 31822765, 2019). "A previous study showed that TTR concentration was substantially decreased in the peripheral blood of individuals with aMCI and AD, indicating that a set of sequester proteins, including TTR, can discriminate individuals with mild cognitive decline from healthy controls." (PMID 30618720, 2018). "Blood concentrations of TTR and ApoA1—proteins whose reduced levels are markers of early-stage cognitive decline—increased after the CGA treatment, which might reflect the improved cognitive functions observed in the neuropsychological tests." (PMID 30241302, 2018). "Patients with ATTRv generally have lower serum TTR levels than non-ATTRv controls, and CNS involvement, including cognitive decline, is a common complication of ATTRv." (PMID 40717228, 2025).
familial hypercholesterolemia (12 papers, 2013 to 2025). An inheritable form of hyperlipidemia, in which there are excess lipids in the blood. "These evidences lend support to the decrease of RBP4 and TTR in human serum associated with hypercholesterolemia." (PMID 27103892, 2015). "In 2009, three novel drugs entered clinical evaluation, two of which, ALN-TTR01 and TKM-ApoB were SNALP-based delivery systems targeting hepatocytes and formulated with anti- Transthyretin (TTR) and anti-ApoB siRNAs in ATTR and hypercholesterolemia patients, respectively." (PMID 26056574, 2014). "Six proteins including retinol-binding protein 4 (RBP4), transthyretin (TTR), gelsolin, haptoglobin, complement factor B (CFB) and CD5 antigen-like protein (CD5L) were identified to play imperative roles in lipid metabolism and inflammatory processes as a consequence of hypercholesterolemia." (PMID 27103892, 2015).
Cerebral ischemia (11 papers, 2013 to 2023). Restriction of arterial blood supply to the brain associated with insufficient oxygenation to support the metabolic requirements of the tissue. "A neuroprotective role of TTR has also been described under conditions of cerebral ischemia in mice deficient for heat shock transcription factor 1 (HSF1), an activator of heat-shock proteins." (PMID 33362465, 2020). "TTR has been shown to increase in cerebrospinal fluid after experimental brain ischemia in mice and neuroprotective and neuroregenerative properties have been proposed." (PMID 37420193, 2023). "Under conditions of compromised heat-shock response, TTR from CSF contributes to control neuronal cell death, edema and inflammation, thereby influencing the survival of endangered neurons in cerebral ischemia." (PMID 33362465, 2020). "For instance, it is described that in situations of compromised heat-shock response, and as a response to cerebral ischemia, CSF TTR contributes to control neuronal cell death, edema and inflammation." (PMID 26837706, 2016). "In addition, the T4 serum transport protein, transthyretin, was found to be neuroprotective in the setting of brain ischemia indicating that it rapidly penetrates the blood brain barrier." (PMID 34829942, 2021). "The neuroprotective role of TTR has been widely documented in animal models of cerebral ischemia." (PMID 33212973, 2020). "However, little is known regarding the downstream signaling pathways triggered by wild-type TTR in the CNS either in neuroprotection of cerebral ischemia or in physiological conditions." (PMID 27518433, 2016). "In addition, we demonstrate that TTR neuroprotective role in a focal cerebral ischemia model is also megalin-dependent." (PMID 27518433, 2016). "This allows us to speculate that TTR action over IGF-IR levels in neurons explains in part some of the neuroprotective properties that have been attributed to TTR in different models of cerebral ischemia or AD." (PMID 25084758, 2015). "TTR can also be internalised by at least some neurons such as hippocampal neurons, where it subsequently acts as a ligand-independent, neurotrophic, and neuroprotective factor following cerebral ischemia, by stimulating neuritogenesis and neuronal recovery through the MAPK pathway." (PMID 31873158, 2019). "Thus damaged choroid plexus with impaired blood-CSF barrier in the course of brain ischemia might impact on thyroid hormone distribution in the CSF (and finally in brain tissue) with TTR." (PMID 28636639, 2017). "Previous work on TTR null mice indicated the potential neuroprotective role of TTR in cerebral ischemia in absence of a full heat-shock response and contributes to control neuronal cell death, edema and inflammation, thereby influencing the survival of endangered neurons in cerebral ischemia." (PMID 23844025, 2013).